HIF1A (hypoxia inducible factor 1 subunit alpha)
Diseases named in the same sentence as HIF1A in open-access papers (continued):
Sharing a sentence is not in itself a finding about the gene and the disease.
tumor (continued). "Because the expression of d2EGFP (half-life ≅ 2 h) requires stabilized HIF-1α and/or HIF-2α, these models are best suited for identifying hypoxic tumor cells around the time of observation or analysis." (PMID 29510720, 2018). "HIF-1α increases tumor angiogenesis by inducing VEGF and other proangiogenic factors that contribute to a highly aggressive tumor phenotype." (PMID 29725496, 2018). "Here, we adopted siHIF‐1α to effectively suppress HIF‐1α, therefore increase CYP450 in hypoxic tumor cells, and further enhance AQ4N activation." (PMID 30128230, 2018). "Clinical data have shown tumor resistance to treatment to receptor tyrosine kinase inhibitors (RTK inhibitors), related to HIF1α overexpression." (PMID 29932118, 2018). "The CMT cells were positive for the epithelial marker, cytokeratin-8; tumor markers, VEGF, HER-2, MMP-2, HIF-1α, and Bcl-2; and hormone receptors, PGR and EPOR, while negative they were for estrogen receptor, ER." (PMID 30410940, 2018). "Hypoxia-induced HIF-1α expression enhances EMT and induces resistance to radiotherapy and chemotherapy, promoting tumor migration and invasion." (PMID 29568752, 2018). "The expression of HIF1α positively correlated with VEGF and PDGF-C expression in tumor samples (P < 0.001)." (PMID 29662659, 2018). "Although both HIF-1α and HIF-2α have long been thought to promote tumor growth, their respective allocated roles have remained ambiguous due to their overlapping and complementary functions." (PMID 29721188, 2018). "Putative pathways proposed to explain that these associations have included enhanced hypoxia inducible factor (HIF)-1α and vascular endothelial growth factor (VEGF) cell expression in the tumor and altered immune functions via intermittent hypoxia (IH)." (PMID 29755400, 2018). "Consistently, the results showed that the protein levels of both HIF-1α and GLUT-1 in LoVo tumor tissues were significantly higher than those in HT29 tissues (0.21 ± 0.006 vs. 0.16 ± 0.2 and 0.96 ± 0.03 vs. 0.69 ± 0.03, respectively, P < 0.05)." (PMID 30546057, 2018). "In our model, we observed liver HIF1α and VEGF expression, whereas tumor cells were positive only for VEGF." (PMID 29795479, 2018). "The reduction of these compounds in tumors with combined HIF-1α and HIF-2α silenced, together with the profound delay in tumor initiation and reduction in tumor growth from these cells, support their investigation as novel targets in TNBC." (PMID 29632647, 2018). "Like all cytotoxic therapies, PDT stimulates the expression of hypoxia-inducible factor-1 alpha (HIF-1α) which increases secretion of vascular endothelial growth factor (VEGF), a key player in the formation of blood vessels and subsequent tumor regrowth." (PMID 30423822, 2018). "This holds true also for CLL where the overexpression and activation of HIF1α in the LN increases ADO generation and signaling, affecting tumor and host cellular responses." (PMID 29649100, 2018). "In fact, HIF-1α and HIF-2α play a crucial role in the tumor growth and tumor progression, respectively." (PMID 30144808, 2018). "HIF-1α can also regulate the c-MET/HGF pathway, which can induce tumor angiogenesis through stimulation of endothelial cell (EC) proliferation, migration, and tubulogenesis." (PMID 29560266, 2018). "The analysis of HIF1α and VEGF mRNA levels of isolated monocytes from healthy donors, after IH in an in vitro model, corroborated the switch to the tumor-promoting phenotype observed in OSA monocytes, exhibiting high levels of both HIF1α and VEGF." (PMID 29997451, 2018). "Hypoxia-inducible factor-1α (HIF-1α) is the subunit of HIF-1, which plays a critical role in tumor growth, angiogenesis and apoptosis." (PMID 30213130, 2018). "The expression levels of HIF-1α, HIF-2α, and downstream genes were assessed according to ascorbate content in the tumor tissue." (PMID 30555801, 2018).
tumor (continued). "Hypoxia not only contributes to tumor formation but is also involved in developing chemoresistance in GBM37, in part through activating hypoxia-inducible factor-1 alpha (HIF-1α) expression and its downstream signaling pathways." (PMID 30262908, 2018). "So we examine the expression of pElk-1, Elk-1, mTOR, HIF-1α, VEGF-A in HUVECs, which were treated by tumor supernatant and inhibitors." (PMID 30250188, 2018). "This is why the percentage of tumor cell death by TSA treatment looks like decreased by HIF-1α overexpression, which was overcome by mutant HIF-1α (K674R) overexpression." (PMID 29416751, 2018). "The IH environment increases HIF1α, and subsequently VEGF, in monocytes, switching them to a tumor-promoting phenotype." (PMID 29997451, 2018). "An increasing amount of evidence demonstrates that hypoxia inducible factor-1α (HIF-1α) is the main upstream inducer of VEGFA, which plays a key role in tumor angiogenesis." (PMID 29866133, 2018). "HIF-1α induces the expression of lactate dehydrogenase-a (LDH-A), allowing the tumour cells to generate energy via anaerobic glycolysis." (PMID 29382042, 2018). "Molecular analysis of the tumor tissues showed that melatonin decreased the levels of p-Akt, p-ERK, cyclin D1, PCNA, Bcl-2, Vimentin, Snail, HIF-1α, and VEGF, but upregulated the expressions of Bax and E-cadherin." (PMID 29725496, 2018). "In vivo experiments show that HIF1-α and HIF2-α are both crucial for macrophage infiltration and immune suppression in tumours, as their separate ablation led to reduced tumour growth." (PMID 29362402, 2018). "The positive area percentage of HIF-1α expression in LoVo and HT29 tumor tissues were 11.4% and 9.1%, respectively." (PMID 30546057, 2018). "TSA acetylated HIF-1α at K674, which led to the activation of VEGF-HRE activity and the inhibition of tumor cell death." (PMID 29416751, 2018). "HIF-1a and HIF-2a are the major components of a transcriptional complex, through which tumor cells adapt to hypoxic conditions." (PMID 29765155, 2018). "CSC factors like c-Myc or Notch are tightly regulated together with Oct4 by the competitive cooperation of HIF-1α and HIF-2α in hypoxic tumor cells." (PMID 30111297, 2018). "The large study including 208 GBM samples evaluated tumor angiogenesis by the expression of CD34, PDGF-C, VEGF and CD105 markers and their relation to HIF1α expression." (PMID 29662659, 2018). "VEGF, VEGFR1, HIF-1α, TWIST1 and MVD expression was heterogeneous for intensity and expression patterns in the different tumor samples examined." (PMID 29716631, 2018). "miR-153 can inhibit both the HIF1α/VEGFA and ANG1/Tie2 pathways to suppress tumor growth and angiogenesis." (PMID 29959560, 2018). "Overexpression of miR-21 induced tumor angiogenesis by targeting PTEN, which in turn activated AKT and ERK signaling and finally enhanced HIF-1α and VEGF expression in prostate cancer cells." (PMID 29415727, 2018). "Enforced expression of TMEM207 abrogated the binding of WWOX to HIF‐1α, increased HIF‐1α and GLUT‐1 expression, even under normoxic conditions, and promoted tumour growth in a xenoplant assay using SAS tongue squamous cancer cells." (PMID 29164763, 2018). "Liu and Colleagues described MDSCs’ differentiation into the tumour-suppressing M1 subtype after SIRT1 induction, and this differentiation occurred as a result of mTOR/HIF-1α-dependent glycolytic reprogramming." (PMID 29362402, 2018). "Recent studies proved that some oncogenes and tumour suppressors, such as PTEN, HIF-1a, Myc, KLF4, FOXM1, and Gas1 regulate glycolysis in cancer cells." (PMID 29463261, 2018).
tumor (continued). "Given that HIF-1α regulates, in addition to metastasis, several other cellular processes, including cell survival, metabolic reprogramming, and angiogenesis, Parkin may exert its tumor suppressive function by inhibiting these processes, which should be addressed in future studies." (PMID 29941042, 2018). "Representative images of immunohistochemical staining for HIF-1α, P-PRAS40, P-RPS6 and Iba1 from FFPE tumor specimens of below and equal to (low) and above (high) median marker frequency." (PMID 30129426, 2018). "Tumours in the TP53INP1‐silenced group expressed more Snail, VE‐cadherin, MMP2 and HIF‐1α protein than the control group tumours." (PMID 29655255, 2018). "The up-regulation of HIF-1α elevates overexpression of VEGF and other pro-angiogenic factors, which protect tumor endothelium and confer radioresistance." (PMID 29507692, 2018). "A recent study revealed that HIF-1α guided CD8 + T-cell migration and function, whereas its depletion on T cells resulted in increased tumor growth and impaired antitumor control." (PMID 29765155, 2018). "However, the ability of elevated Hif-1α to permit cell survival following chromosome missegregation raises the possibility that adapting to hypoxic conditions during the early avascular phase of tumor development may also permit aneuploidy tolerance." (PMID 30332653, 2018). "Taken together, MMP-13 over-expression was triggered by hypoxia/HIF-1α as an important mechanism to induced EMT and tumor invasion in NPC." (PMID 29515112, 2018). "Inactivation of HIF-1α from lysozyme 2 (LysM)-positive neutrophils and macrophages in MMTV-PyMT mice led to hindered tumor progression and smaller tumors." (PMID 29896451, 2018). "Our study showed that expression of both mentioned factors (HIF1A and VEGFA) was the highest et the early stage of tumor development." (PMID 30412628, 2018). "The cross-talk between HIF-1α and ERα converges at KDM4B, which is important for cell cycle progression and tumor growth in ER positive breast cancer." (PMID 29342868, 2018). "For example, hypoxia upregulates hypoxia inducible factor 1-alpha (HIF1α)-dependent ADAM10 expression resulting in MHC class I polypeptide-related sequence A (MICA) shedding from the surface and decreased lysis of tumor cells." (PMID 29963058, 2018). "A bivariate two-sided Spearman’s rank correlation showed a significant correlation between HIF-1α mRNA and EGFR mRNA expression in tumor tissues (correlation coefficient: +0.69; p < 0.001)." (PMID 30513863, 2018). "Septin 9 is capable of interacting with the hypoxia-inducible factor 1 alpha HIF-1α acting as a positive regulator in the hypoxic pathway leading to increased proliferation, soft agar clonal survival and tumor growth." (PMID 29699512, 2018). "Recently, OA has been proven to have a radiosensitizing effect on hypoxic tumor cells through the downregulation of intracellular GSH content and HIF-1α expression." (PMID 30246018, 2018). "Intuitively, suppression of HIF-1α in MM cells downregulates pro-angiogenic genes including VEGF and subsequently reduces tumour burden in both subcutaneous and intratibial mouse models of MM." (PMID 29098360, 2018). "This is largely because of the hypoxic tumor microenvironment, and the increased expression of Poly(ADP-ribose) polymerase (PARP) and Hypoxia Inducible Factor 1a (HIF-1a)." (PMID 29538310, 2018). "We found that treatment with MET NVB + Endo was most effective in inhibiting tumor growth, decreasing expression of CD31, VEGF, HIF-1α, and CEPs, and reducing side effects, inducing apoptosis, such as expression of Bcl-2, Bax and caspase-3." (PMID 30305062, 2018). "HIF1α, another STAT3-dependent gene, mediates the differentiation into tumor-infiltrating macrophages." (PMID 30075733, 2018).
tumor (continued). "It correlated with qPCR results showing the highest expression of HIF1A and VEGFA in the first time-points of tumor growth (4 days)." (PMID 30412628, 2018). "The results show that HIF-1α level was low in B16-F10 treated with HMSNs@PFC/O2@C, indicating that the nanoparticles carried O2 and modulated the hypoxic tumor microenvironment." (PMID 30487569, 2018). "We observe the effect of LCMV infection on the expression of HIF-1α and HIF targets, as well as on different properties of tumor cells." (PMID 29560117, 2018). "Mechanistically, the expression of HIF-1α and GLUT-1 in LoVo cells and LoVo tumor tissues was remarkably higher than in HT29 cells and tissues." (PMID 30546057, 2018). "This pro-survival role of 14-3-3ζ in stabilizing HIF1α is necessary for hypoxia-induced expression of genes, including those indicative of EMT, which leads to tumor metastasis." (PMID 29915393, 2018). "mTOR induce transcription of many genes involved in aerobic glycolysis and tumor growth, including HIF-1α, nuclear factor-κB, and c-Myc, among which HIF-1a was previously demonstrated to be inhibited by Sal-B treatment." (PMID 29789538, 2018). "The expression levels of SIRT3 were lower in the cancer patient tissues but higher in normal tissues, while the expression levels of STAT3, HIF‐1α, GLUT1, LDHA, and HK2 were higher in tumor tissues but lower in normal tissues." (PMID 30094960, 2018). "Immunohistochemistry on tissue microarrays (TMA) was performed to demonstrate expressions of PD-L1, HIF-1α, and HIF-2α in tumor cells and PD-1, CD4, and CD8 in lymphocytes to assess lymphocyte density in tumor microenvironment." (PMID 30144808, 2018). "The hypoxic tumor milieu induces the upregulation of VEGF gene expression, mediated by the activation of the hypoxia-inducible factor 1α (HIF1α), creating a VEGF gradient that provides chemotactic signals for the sprouting of vascular cells." (PMID 28662055, 2017). "HIF-2α has been demonstrated to be more important in RCC tumorigenesis than HIF-1α, since blocking HIF-2α results in a strong reduction of RCC tumor formation and angiogenesis." (PMID 28903416, 2017). "In summary, we report that miR-199a-5p plays a tumor-suppressive role by directly targeting HIF-1α and thereby suppresses genes downstream of HIF-1α, such as VEGF, CXCR4, BNIP3 and BCL-xL." (PMID 29137361, 2017). "In contrast, both HIF-1α and CA9 were clearly expressed in all of the pre-Bev initial and post-Bev recurrent tumors, suggesting that tumor oxygenation was improved with Bev treatment but returned to the original hypoxic condition in tumors refractory to Bev." (PMID 29262608, 2017). "Immunohistochemical tests were applied to detect the expressions of Bcl-2, Bax, HIF-1α, and VEGF in tumor tissues." (PMID 29348766, 2017). "Among them, we identified that PD-1 expression in tumor-infiltrating lymphocytes was HIF-1α dependent, an important observation given that PD-1 identifies the patient-specific CD8+ tumor-reactive TIL repertoire." (PMID 29136509, 2017). "Two weeks after the cell injection, tumor-bearing mice received treatments with DDP, si-HIF-1α, or DDP/si-HIF-1α." (PMID 28790395, 2017). "At sacrifice, the average tumor size of the control, DDP, si-HIF-1α, and combination groups were 1413 mm3, 932 mm3, 636 mm3, and 296 mm3, respectively." (PMID 28790395, 2017). "Significant changes in tumor angiogenesis, cancer cell proliferation, apoptosis, HIF1α levels, HIF-1 target genes, and ABCG2 were found both in vitro and in tumor tissue." (PMID 29333297, 2017). "HIF‐1α and HIF‐2α protein were detected in most types of human tumours, including pancreatic, bladder, colon, breast, glial, hepatocellular, prostate and renal tumours." (PMID 28544376, 2017). "Both HIF1α and XIAP expression have been correlated with the progression or severity of neoplastic disease." (PMID 28666324, 2017).
tumor (continued). "The expression levels of four genes, HIF1A, MTHFD1, GGH and TYMS, in tumor tissues can predict the response to preoperative CRT including either S-1 or UFT/LV." (PMID 28417167, 2017). "Overexpression of miR-21 in DU145 cells enhanced HIF-1α and VEGF expression and induced tumor angiogenesis." (PMID 28052006, 2017). "Although HIF-1α primarily contributes to promoting EMT and tumor progression, the role of HIF-2α needs to be considered as HIF-2α exhibits a distinct role in hypoxic expression and activation of target genes." (PMID 28977889, 2017). "Downstream targets of hypoxia-induced, oxygen-dependent HIF-1α include VEGF and GLUT1, and transactivation of these targets contributes to tumor angiogenesis and glucose metabolism." (PMID 28467517, 2017). "Co-inmunofluorescence analysis also confirmed co-expression of HIF-1α and CAIX in the same tumor cells." (PMID 28099149, 2017). "Next, we examined mRNA expression of HIF1α, EPO and Cyclin D1 in the tumor tissues from the initial 14 patients whose serum EPO dropped after tumor resections." (PMID 29137269, 2017). "We further analyzed the clinical data to predict the roles of HIF-1α, HIF-2α, and HAF in tumor progression and survival rate." (PMID 28572533, 2017). "MiR-30e also inhibited tumor growth and suppressed expression of IRS1, AKT, ERK1/2 and HIF-1α in mouse xenograft tumors." (PMID 29162879, 2017). "Consistently, increased miR-135b expression was positively correlated with HIF-1α expression and microvessel density in a model of HNSCC, which affected tumor metabolism." (PMID 28977937, 2017). "Specifically, we have studied the effect of AZD5363 on the levels of pro‐angiogenic proteins VEGF and hypoxia‐inducible factor 1‐alpha (HIF‐1α) and the subsequent impact of any alteration on tumour vascularity and oxygenation." (PMID 29084756, 2017). "NFATC4 regulates HIF-1A/VEGF signaling and acts as a transcription factor that regulates cell survival, differentiation, angiogenesis, invasive migration, and the tumor microenvironment." (PMID 29253018, 2017). "In contrast, in HIF-1α KO mice, delivery of recombinant sVEGFR1 rescued growth of MC38 tumours, along with an increase in pericyte coverage and tumour oxygenation as well as decrease in tumour cell death." (PMID 29150606, 2017). "Recent work has demonstrated that HIF-1α promotes the expression of LOXL2, which is believed to amplify tumor aggressiveness." (PMID 28449718, 2017). "This interaction increased HIF-1α protein stability and HIF-1 transcriptional activity in vitro and promoted proliferation, tumor growth and angiogenesis in vivo." (PMID 28380438, 2017). "Regarding geographic distribution of immunostained cancer cells within the tumor sections, positivity for HIF-1α, as well as for CAIX, MCT4 and MCT1 were detected in perinecrotic areas and in the center of tumor nests likely in relation with hypoxia." (PMID 28099149, 2017). "HIF-1α directly regulates HCC development and IL-8 assisted tumor growth through regulation of angiogenesis in the vascular endothelial system s." (PMID 28053598, 2017). "In the log-rank test, deep tumor location, MIB-1 positivity, large tumor size (≥5 cm), and HIF-1α positivity were significant poor prognostic factors." (PMID 28558056, 2017). "In ovarian cancer cells, NOX4-derived ROS together with mitochondrial-derived ROS are necessary for tumor-induced angiogenesis and regulation of VEGF level through HIF-1α expression." (PMID 28626501, 2017). "HIF‐1α protein and HIF‐2α protein were detected in most types of human tumours, including pancreatic, bladder, colon, breast, glial, hepatocellular, prostate and renal tumours." (PMID 28544376, 2017).